TLK2 (tousled like kinase 2)
Description:
Serine/threonine-protein kinase involved in the process of chromatin assembly and probably also DNA replication, transcription, repair, and chromosome segregation. Phosphorylates the chromatin assembly factors ASF1A and ASF1B. Phosphorylation of ASF1A prevents its proteasome-mediated degradation, thereby enhancing chromatin assembly. Negative regulator of amino acid starvation-induced autophagy.
Synonyms: PKU-ALPHA; MGC44450; HsHPK; MRD57
Tractability: Small molecule: a structure with a bound ligand is known; a high-quality ligand is known; it belongs to a druggable protein family. PROTAC: ubiquitination databases record sites on it; its protein half-life has been measured; a small molecule that binds it is known.
Target class: Other protein kinase TLK family; Protein Kinase; Kinase; Enzyme; Other protein kinase group
Gene: Protein-coding gene on chromosome 17 (62,458,658 to 62,615,481, forward strand). Ensembl gene ENSG00000146872.
Subcellular location: Nucleus; Nucleus, nucleoplasm; Cytoplasm, perinuclear region; Cytoplasm, cytoskeleton
Subcellular location (Human Protein Atlas): Nucleoplasm; Nucleoli
Gene Ontology:
Molecular function: ATP binding; identical protein binding; protein binding; protein serine kinase activity; protein serine/threonine kinase activity; protein kinase activity
Biological process: chromosome segregation; negative regulation of proteasomal ubiquitin-dependent protein catabolic process; nucleus localization; intracellular signal transduction; negative regulation of autophagy; regulation of chromatin organization
Cellular component: intermediate filament; nucleolus; nucleoplasm; nucleus; perinuclear region of cytoplasm; cytoskeleton
Genetic constraint (gnomAD): Loss-of-function variants: 4 observed, 89.12 expected, observed/expected ratio (o/e) 0.0449, 90% interval 0.021 to 0.1. The upper end of that interval is the gene's LOEUF score, 0.1, which puts it in group 1 of 6, group 1 being the genes least tolerant of losing a copy. Missense variants: 257 observed, 746.91 expected, observed/expected ratio (o/e) 0.34, 90% interval 0.31 to 0.38. Synonymous variants: 223 observed, 267.45 expected, observed/expected ratio (o/e) 0.83, 90% interval 0.75 to 0.93.
Gene-disease validity (ClinGen):
ClinGen rates the evidence that TLK2 causes each of these diseases.
complex neurodevelopmental disorder (autosomal dominant): Definitive. A disorder that involves more than one phenotype associated with the central nervous system, including but not limited to intellectual disability, autism, and seizures (epilepsy).
Homologues: Orthologues: macaque TLK2 (99% identical), pig TLK2 (99% identical), rabbit TLK2 (99% identical), dog TLK2 (99% identical), rat Tlk2 (99% identical), mouse Tlk2 (99% identical), guinea pig TLK2 (98% identical), chimpanzee TLK2 (97% identical), tropical clawed frog tlk2 (89% identical), zebrafish tlk2 (81% identical), Drosophila melanogaster Tlk (53% identical), Caenorhabditis elegans tlk-1 (46% identical). Paralogues in human: TLK1 (73% identical), TTK (20% identical).
Diseases named in the same sentence as TLK2 in open-access papers:
TLK2 is named in the same sentence as 42 diseases in open-access papers, as found by Europe PMC text mining. Sharing a sentence is not in itself a finding about the gene and the disease. The quoted sentences say what the papers report.
breast carcinoma (9 papers, 2015 to 2026). "TLK2 has been implicated in the pathogenesis of various types of cancer, including breast cancer, glioblastoma, and acute myeloid leukemia (AML)." (PMID 41878536, 2026). "One potentially druggable target gene closely linked to adverse clinical events in breast cancer patients is TLK2." (PMID 32408897, 2020). "In luminal breast cancer, TLK2 overexpression interfered with the Chk1/2-induced G2/M DNA damage checkpoint signaling, which leads to prolongation of the DNA repair process and has an adverse effect on chromosome stability, thus inducing carcinogenesis." (PMID 38343446, 2023). "TLK2 enhances the aggressiveness of breast cancer through the activation of the EGFR/SRC/FAK signaling pathway." (PMID 38343446, 2023). "Emerging evidence suggests that TLK2 can promote cancer invasiveness by enhancing the migration and invasion of breast cancer and glioblastoma cell." (PMID 35064619, 2022). "We further evaluated the efficacy of pharmacological inhibition of TLK2 on breast cancer cell lines." (PMID 32408897, 2020). "Our case study of the 17q23 region demonstrates that PPH exerts antineoplastic effects in breast cancer cells, at least in part, through the pharmacological targeting of TLK2-mediated DDR pathway." (PMID 32408897, 2020). "Our study is the first comprehensive analysis of TLK2 function in aggressive luminal breast cancers, which will timely complement the CPTAC paper." (PMID 27694828, 2016). "Among all the breast cancer subtypes, luminal B breast cancers most frequently harbour TLK2 amplifications (21.3%), and also present the highest TLK2 expression level." (PMID 27694828, 2016). "To examine the cell signalling changes following TLK2 overexpression in the T47D breast cancer cells, we performed western blot analysis of an array of signalling molecules in breast cancer." (PMID 27694828, 2016). "Together, these data provided a proof of concept for the therapeutic value of TLK2 inhibition in TLK2-amplified breast cancers." (PMID 27694828, 2016). "Taken together, these facts position TLK2 as an attractive cell cycle kinase target for more aggressive luminal breast cancers that harbour TLK2 amplifications." (PMID 27694828, 2016). "Conversely, TLK2 inhibition selectively inhibits the growth of TLK2-high breast cancer cells, downregulates ERα, BCL2 and SKP2, impairs G1/S cell cycle progression, induces apoptosis and significantly improves progression-free survival in vivo." (PMID 27694828, 2016). "More important, breast cancer cells that harbour TLK2 amplifications appear to have been addicted to TLK2 overexpression, so that TLK2 knockdown causes potent growth inhibition and induction of apoptosis." (PMID 27694828, 2016). "Here we discovered that TLK2 overexpression endows enhanced invasiveness of luminal breast cancers, and appears to be addictive for TLK2-amplified breast cancers so that TLK2 inhibition renders decreased cancer cell viability and increased apoptosis." (PMID 27694828, 2016). "Future studies will be required to further evaluate the therapeutic effect of TLK2 inhibition in patient-derived xenograft tumour models, and ultimately in clinical trials of breast cancer." (PMID 27694828, 2016). "Applying this analysis to the genomic data from The Cancer Genome Atlas (TCGA) nominated a new oncogene target called tousled-like kinase 2 (TLK2) frequently amplified in aggressive luminal breast cancer." (PMID 27694828, 2016). "To examine the prognostic effect of TLK2 overexpression (OE), we analysed the available survival data for TCGA breast cancer patients and compared the group of patients with TLK2-high tumours versus the rest." (PMID 27694828, 2016). "Silencing of TLK1 or TLK2 appears to result in distinct cell cycle alterations and different effects on apoptosis in luminal breast cancer cells overexpressing TLK2." (PMID 27694828, 2016).
breast carcinoma (continued). "In this study, ConSig-Amp analysis nominated TLK2 as a candidate kinase target upregulated by genomic amplifications in more aggressive form of luminal breast cancers." (PMID 27694828, 2016). "TLK2 is amplified/upregulated in 26 % of sporadic breast cancer cases, and confers significantly poor survival (p = 0.00072)." (PMID 26427375, 2015). "TLK2 is amplified/upregulated in 26 % of sporadic breast cancer cases, and its amplification/upregulation is mutually exclusive to BRCA2 deletion/downregulation." (PMID 26427375, 2015). "Furthermore, Tousled-like kinase 2 (TLK2), a cell cycle-regulating kinase, exhibits a higher frequency of amplification in luminal B breast cancer." (PMID 39429474, 2024). "The overexpression of TLK2 has been shown to augment the invasiveness of breast cancer cells." (PMID 39429474, 2024). "Moreover, frequent amplification of TLK2 has been found in luminal breast cancers that express the estrogen receptor (ER)." (PMID 37446279, 2023). "Therefore, we assessed the growth-inhibitory effect of three PTZs in a panel of nine breast cancer and immortalized cell lines exhibiting respective copy-number and protein levels of TLK2." (PMID 32408897, 2020). "In addition, frequent TLK2 amplifications were identified in oestrogen receptor (ER)-positive luminal breast cancers and TLK2 inhibition, alone or in combination with tamoxifen, substantially inhibited the growth of MCF7 xenograft tumours." (PMID 29955062, 2018). "TLK2 is mostly amplified in ER+ breast cancers, which are commonly treated with endocrine therapy." (PMID 27694828, 2016). "The selective effect of TLK2 inhibition against TLK2-high breast cancer cells as compared with benign breast epithelial cells suggests a possible more selective cellular effect of TLK2 inhibitors as compared with the inhibitors of other cell cycle kinases that do not show cancer cell specificity." (PMID 27694828, 2016). "Taken together, these data suggest that EGFR/SRC/FAK axis may be important in TLK2-driven invasiveness in breast cancer cells, and TLK2 may engage this axis via interaction with SRC." (PMID 27694828, 2016). "This suggests that TLK2 may serve as an attractive genomic target for the aggressive luminal breast cancers harbouring TLK2 amplifications." (PMID 27694828, 2016). "Next, we went on to examine the effect of TLK2 silencing on breast cancer cell growth." (PMID 27694828, 2016). "One possibility is that RPS6KB1 is frequently co-amplified with TLK2, which may provide additional genetic background for the action of endogenously overexpressed TLK2 in breast cancer cells." (PMID 27694828, 2016). "Ectopic expression of TLK2 leads to enhanced aggressiveness in breast cancer cells, which may involve the EGFR/SRC/FAK signalling." (PMID 27694828, 2016). "In addition, we observed a selective effect of TLK2 inhibition on TLK2-high breast cancer cells versus TLK2-low breast cancer cells or benign breast epithelial cells." (PMID 27694828, 2016). "Besides luminal breast cancer cells, TLK2 is also overexpressed in a few ER-negative breast cancer cell lines." (PMID 27694828, 2016). "Thus these two cell lines will be ideal to study the effect of TLK2 inhibition in TLK2-amplified luminal breast cancer cells with different Her2 status." (PMID 27694828, 2016). "Our data showed that ectopic overexpression of TLK2 in the T47D luminal breast cancer cells markedly increased cell migration and invasion, whereas withdrawal of TLK2 expression eliminated this effect, suggesting the direct role of TLK2 in enhanced invasiveness." (PMID 27694828, 2016). "However, inhibiting TLK2 leads to the downregulation of ERα, BCL2, and SKP2, causing cell cycle arrest in the G1/S phase and ultimately triggering apoptosis, which can help improve the prognosis of patients with breast cancer." (PMID 38343446, 2023). "Furthermore, we found that TLK2 may involve the EGFR/SRC/FAK axis to enhance breast cancer cell invasiveness." (PMID 27694828, 2016).
breast carcinoma (continued). "This revealed several known kinase targets in breast cancer such as ERBB2, PAK1, RPS6KB1 and PTK2 (refs 16, 17), together with a new candidate kinase target, TLK2." (PMID 27694828, 2016). "Among the TLK2-high breast cancer cell lines, MCF7 and MDAMB361 show the highest TLK2 expression level, and also harbour high levels of TLK2 amplifications." (PMID 27694828, 2016). "To extend the potential use of TLK2 inhibitor in clinical samples, we examined the efficacy of PPH on ex vivo cultures of circulating tumor cells (CTCs) isolated from blood samples of nine breast cancer patients." (PMID 32408897, 2020). "High-TLK2 expression was observed in multiple breast cancer cell lines (particularly ER+/Her2− lines), but not in benign breast epithelial cells." (PMID 27694828, 2016). "Copy-number data from TCGA show that TLK2 is amplified in about ∼9% of all breast cancers, and such events are more frequent in ER-positive than negative breast cancers (10.5 versus 2.9%)." (PMID 27694828, 2016). "TLK2 amplification is independent of most known amplified oncogenes in breast cancer (that is, HER2, CCND1 and MYC), except RPSKB1." (PMID 27694828, 2016). "MTT cell proliferation assays revealed that specific silencing of TLK2 by esiRNA or siRNA potently inhibited the growth of TLK2-high breast cancer cells (MCF7, MDAMB361 and CAMA1), but not that of the TLK2-low luminal ZR75-1 breast cancer cells or MCF12A and MCF10A benign breast epithelial cells." (PMID 27694828, 2016). "However, these cell lines typically do not harbour high TLK2 amplifications, and TCGA copy-number data suggest that TLK2 amplifications are much more frequent in ER-positive than negative breast cancers, 10.5% versus 2.9%." (PMID 27694828, 2016). "This suggests that TLK2 is frequently co-amplified with RPS6KB1, but not with other known amplified genes in breast cancer such as ERBB2, MYC, CCND1, and so on." (PMID 27694828, 2016). "With induction of TLK2 inhibition, decreased colony-forming ability was observed only in the TLK2-high MCF7 and MDAMB361 luminal breast cancer cells, but not in the TLK2-low T47D luminal breast cancer cells, as shown by clonogenic assays." (PMID 27694828, 2016).
glioblastoma (4 papers, 2022 to 2026). The most malignant astrocytic tumor (WHO grade IV). "In glioblastoma, TLK2 overexpression correlates with poor clinical outcomes and drives cell proliferation, migration, invasion, and epithelial-mesenchymal transition through the SRC signaling pathway, while silencing TLK2 has opposite effects." (PMID 38343446, 2023). "TLK2 is reported to complex with Src and activate EGFR/Src/FAK signalling pathway to promote the migration and invasion in breast adenocarcinoma and glioblastoma cells." (PMID 35064619, 2022). "It has been recently reported that the TLK1 paralog, TLK2, could form a complex with Src and activate the EGFR/Src/FAK signaling pathway to promote the migration and invasion of breast adenocarcinoma and glioblastoma cells." (PMID 36497211, 2022).
Intellectual disability (4 papers, 2018 to 2025). "While TLK1 and TLK2 share overlapping roles in genome integrity, mutations in TLK2 have been linked to neurological disorders and intellectual disabilities." (PMID 39796704, 2024). "We show that TLK2 mutations involved in intellectual disability impair kinase activity, and the docking of several small-molecule inhibitors of TLK activity suggest that the crystal structure will be useful for guiding the rationale design of new inhibition strategies." (PMID 29955062, 2018). "Also, the inherited variant in TLK2 (MIM: 618050) in individual 50 might contribute to her intellectual disability and hypotonia." (PMID 39668183, 2025). "Interestingly, SNPs in TLK1 have been associated with mathematical ability in GWAS studies, whereas pathogenic mutations in TLK2, a paralog of TLK1, have been reported in patients with ASD, intellectual disability (ID), schizophrenia, and microcephaly." (PMID 34069769, 2021).
breast tumours (2 papers, 2015 to 2016). "As most ER+ breast tumours are treated with endocrine therapy, we also examined the combination effect of TLK2 inhibition together with tamoxifen, the most commonly used endocrine agent." (PMID 27694828, 2016). "This suggests that TLK2 may play a role in modulating ERα protein level in breast tumours, whereas the BCL2 response may be an effect specific to TLK2 inhibition." (PMID 27694828, 2016). "In particular, GOBO-based analysis indicates that TLK2 is overexpressed in 37 % luminal (estrogen receptor (ER)-positive) breast tumours, and grade 3-stratified multivariate analysis indicates a hazard ratio of 2.25 (p = 10−5) and poor survival (p < 0.01) in patients with these tumours." (PMID 26427375, 2015). "Furthermore, our in vivo data suggest that TLK2 inhibition may possess viable therapeutic value in TLK2-amplified luminal breast tumours." (PMID 27694828, 2016). "To examine if TLK2 overexpression upregulates BCL2 and ERα protein level in breast tumour tissues, we compared the BCL2 and ERα protein level in ER-positive breast cancers with or without TLK2 overexpression using the RPPA data available from TCGA." (PMID 27694828, 2016).
gastric cancer (2 papers, 2023 to 2025). A primary or metastatic malignant neoplasm involving the stomach. "Overexpressed TLK2 binds to ATF4 to enhance asparagine synthetase (ASNA) transcription level and prevent ubiquitination of ASNA, thus promoting the progression of gastric cancer (GC) by reprogramming amino acid metabolism." (PMID 38343446, 2023).
adrenocortical carcinoma (1 paper, 2023). "TLK2 overexpression predicted poor OS in adrenocortical carcinoma (ACC) (p < 0.001), LIHC (p = 0.005), and KICH (p = 0.007), while indicating longer OS in thymoma (THYM) (p = 0.008) and KIRC (p = 0.031)." (PMID 38343446, 2023).
craniosynostosis (1 paper, 2018). Craniosynostosis is defined as the premature fusion of one or more cranial sutures leading to secondary distortion of skull shape resulting in skull deformities with a variable presentation. "However, sequence-based screening of 309 DNA samples from individuals with mixed, genetically undiagnosed craniosynostosis (Supplemental Subjects and Methods) did not identify further case subjects, indicating that TLK2 mutations are a rare cause of craniosynostosis." (PMID 29861108, 2018).
leukemia (1 paper, 2026). A malignant (clonal) hematologic disorder, involving hematopoietic stem cells and characterized by the presence of primitive or atypical myeloid or lymphoid cells in the bone marrow and the blood. "Both TLK2 ASO alone and in combination with gilteritinib significantly reduced spleen size, leukemia burden, and bone marrow progenitor cell populations." (PMID 41878536, 2026).
lung carcinoma (1 paper, 2023). "However, there are no reports on the function of TLK2 in the context of lung cancer." (PMID 37185598, 2023).
neuroblastoma (1 paper, 2026). Neuroblastoma (NB) is the most common solid, extracranial childhood tumor. "Similarly, in rat neuroblastoma cells, we found that neuronal differentiation enhances a cytoplasmic pool of TLK2 by two mechanisms: nuclear export of full length TLK2 and increased expression of TLK2 splice variants lacking the NLS." (PMID 42023051, 2026).
serous ovarian cancer (1 paper, 2025). "Similarly, in UWB1.289, a BRCA1-mutant high-grade serous ovarian cancer (HGSOC) cell line, TLK1 or TLK2 depletion decreased sensitivity to olaparib and niraparib." (PMID 39844055, 2025).
synucleinopathies (1 paper, 2026). "Collectively, these results indicate that TLK2 activation plays a key cytotoxic role in a-synucleinopathies." (PMID 41507136, 2026).
West syndrome (1 paper, 2020). "The clinical presentation of our patient shows similarities with the previously reported patients carrying heterozygous TLK2 variants, however the symptoms are more severe and complicated with additional features, such as cerebellar vermis hypoplasia and West syndrome." (PMID 31558842, 2020).